KRT32 (keratin 32)
Synonyms: HHA2; HKA2; KRTHA2; Ha-2; HA2
Tractability: No criterion of Open Targets' tractability assessment is met for any kind of drug.
Gene: Protein-coding gene on chromosome 17 (41,459,513 to 41,467,386, reverse strand). Ensembl gene ENSG00000108759.
Pathways (Reactome):
Developmental Biology: Formation of the cornified envelope; Keratinization
Gene Ontology:
Molecular function: protein binding; structural constituent of skin epidermis; structural molecule activity
Biological process: epidermis development; epithelial cell differentiation; intermediate filament organization; morphogenesis of an epithelium
Cellular component: extracellular exosome; cytoskeleton; cytosol; keratin filament
Genetic constraint (gnomAD): Loss-of-function variants: 43 observed, 38.66 expected, observed/expected ratio (o/e) 1.11, 90% interval 0.87 to 1.43. The upper end of that interval is the gene's LOEUF score, 1.43, which puts it in group 5 of 6, group 1 being the genes least tolerant of losing a copy. Missense variants: 569 observed, 588.19 expected, observed/expected ratio (o/e) 0.97, 90% interval 0.9 to 1.04. Synonymous variants: 235 observed, 247.11 expected, observed/expected ratio (o/e) 0.95, 90% interval 0.85 to 1.06.
Homologues: Orthologues: chimpanzee KRT32 (99% identical), macaque KRT32 (95% identical), dog KRT32 (83% identical), mouse Krt32 (80% identical), pig KRT32 (77% identical), rabbit KRT32 (75% identical), rat Krt32 (74% identical). Paralogues in human: KRT35 (67% identical), KRT36 (66% identical), KRT31 (62% identical), KRT33A (61% identical), KRT33B (61% identical), KRT34 (60% identical), KRT38 (56% identical), KRT39 (56% identical), KRT40 (56% identical), KRT37 (54% identical), KRT14 (46% identical), KRT17 (45% identical), and 56 more.
Diseases named in the same sentence as KRT32 in open-access papers:
KRT32 is named in the same sentence as 11 diseases in open-access papers, as found by Europe PMC text mining. Sharing a sentence is not in itself a finding about the gene and the disease. The quoted sentences say what the papers report.
staphylococcus aureus infection (2 papers, 2020 to 2023). An infectious process in which the bacteria Staphylococcus aureus is present. "KEGG pathway: The bar chart of the KEGG pathways related to the set of genes showed that most genes were involved in Staphylococcus aureus infection (KRT32, C3, KRT38, and KRT37) and the estrogen signaling pathway (KRT32, KRT38, and KRT37)." (PMID 37900279, 2023).
Hyperkeratosis (1 paper, 2024). Hyperkeratosis is a histopathological term defining a thickened stratum corneum and may be present in many different skin conditions, with many possible overlaps. "In our study, we found KRT32 regulates keratinocyte proliferation, as evidenced by the thickened epidermis, and hyperkeratosis with focal parakeratosis observed in Krt32(−/−) mice." (PMID 39048559, 2024).
inflammatory skin disorder (1 paper, 2025). "This concept is supported by studies on other keratin proteins; for instance, loss-of-function mutations in KRT32 lead to hyperactivation of NF-κB signaling and are implicated in the pathogenesis of pityriasis rubra pilaris, an inflammatory skin disorder." (PMID 40766069, 2025).
skin inflammation (1 paper, 2024). "KRT32 is found to be predominantly localized in basal keratinocytes and exhibits an inhibitory effect on skin inflammation by antagonizing the NF-κB pathway." (PMID 39048559, 2024). "Importantly, Krt32 knockout mice exhibit a PRP-like dermatitis phenotype, suggesting compromised anti-inflammatory function of keratinocytes in response to external pro-inflammatory stimuli." (PMID 39048559, 2024). "Therefore, Krt32 knockout may predispose individuals to PRP rather than spontaneous skin inflammation directly." (PMID 39048559, 2024). "However, electron microscopy analysis conducted in the present study demonstrated that loss of KRT32 exerts no discernible impact on the structural integrity of keratinocytes (desmosomes and hemidesmosomes) in the PRP-like dermatitis Krt32(-/-) mice model." (PMID 39048559, 2024). "The findings of vivo experiments indicate that the absence of KRT32 in mice could compromise the anti-inflammatory function of keratinocytes, rendering them less effective at defending against harmful external stimuli and leading to skin inflammation resembling PRP-like manifestations." (PMID 39048559, 2024).
tumor (2 papers, 2016 to 2019). "Notably, the expression of 4 of these genes (TERT, ADPRM, SON and KRT32) were significantly higher in tumor tissues expressing chimeric transcripts compared to tissues without the fusion transcripts (bottom bar graphs)." (PMID 31429776, 2019).
KRT32 also shares sentences with these, for which no sentence is quoted: colorectal cancer (1 paper); dermatitis (1); end-stage renal disease (1); Hyperkalemia (1); Hypokalemia (1); pityriasis rubra pilaris (1).